HK2 (hexokinase 2)
Diseases named in the same sentence as HK2 in open-access papers (continued):
Sharing a sentence is not in itself a finding about the gene and the disease.
ovarian carcinoma (continued). "Because ovarian cancer overexpresses important enzymes, such as pyruvate kinase M2 (PKM2), hexokinase 2 (HK2), and lactate dehydrogenase A (LDHA), there is an increase in glycolytic activity." (PMID 41023769, 2025). "miR-29b negatively regulates the expression of AKT2 and AKT3, downregulates HK2 and PKM2, and reduces the Warburg effect, thereby slowing ovarian cancer progression." (PMID 39609317, 2024). "In ovarian cancer cells, the inhibition of miR-1244 promotes proliferation and aerobic glycolysis (PKM2, HK2, and PDK1) and ROCK1 expression." (PMID 38338859, 2024). "Aurora-A kinase induced a metabolic shift towards glycolysis and altered the expression of glucose metabolic genes such as LDHA and HK2 by participating and influencing the SOX8/FOXK1 signaling axis in ovarian cancer." (PMID 37110218, 2023). "HK2, another glycolytic target of HIF-1α, was found to be overexpressed in BReast CAncer 1 (BRCA1) mutant ovarian cancers." (PMID 37720350, 2023). "The potential correlation between HK2 and EMT-related proteins in human ovarian cancer tissues and OV (ovarian serous cystadenocarcinoma) was confirmed by using Pearson correlation analysis and TIMER 2.0." (PMID 35953860, 2022). "In order to investigate the potential connection between HK2 and tumor prognosis in human ovarian cancer, HK2 was exogenously expressed in human ovarian cancer cell line SKOV3 and knocked down in human ovarian cancer cell line A2780, respectively." (PMID 35953860, 2022). "The impacts of TRPM7 silencing on the levels of glycolysis-related HK2, PDK1 and oxidative phosphorylation (OXPHOS)-related IDH3B and UQCRC1, HIF-1α expression and AMPK phosphorylation were determined in ovarian cancer." (PMID 35101076, 2022). "In parallel, TRPM7 silencing decreased the glucose uptake of tumor-bearing mice and TRPM7 levels were negatively correlated with IDH3B and UQCRC1, but positively with HK2 and PDK1 expression in ovarian cancer tissues." (PMID 35101076, 2022). "By inhibiting HK2 and PKM2 in human ovarian cancer SKOV3 and 3AO cells, Ginsenoside 20(S)-Rg3 decreased tumor cell glycolysis." (PMID 36339566, 2022). "TAMs through lysophosphatidic acid (LPA) are known to induce pseudohypoxia in ovarian cancer cells through HIF1α via Gαi2, Rac1, and NOX2 axis, which results in upregulation of the glycolytic enzyme hexokinase-2 (HK2) and glucose transporter-1 (GLUT1)." (PMID 36358644, 2022). "To understand how TRPM7 modulated metabolic reprogramming in ovarian cancer, we analyzed the expression of TRPM7, glycolysis-related HK2, PDK1, and OXPHOS-related IDH3B and UQCRC1 in 60 ovarian cancer tissues by IHC." (PMID 35101076, 2022). "On the other hand, re-expression of miR-145 in ovarian cancer cells, which is usually downregulated in this cancer, was shown to inhibit the Warburg effect by targeting DNMT3A and hexokinase-2 (HK2)." (PMID 34298969, 2021). "MiR-145 blocked epithelial-mesenchymal transition of ovarian cancer cells by targeting FSCN1, inhibited glutamine metabolism by targeting c-myc, inhibited the Warburg effect by targeting HK2, and regulated RNA methylation by targeting YTHDF2." (PMID 33419459, 2021). "In the course of exploring the sensitivity of ovarian cancer cells to cisplatin, this study first proposed the role of UBA domain of p62 in regulating the recruitment of HK2 to mitochondria." (PMID 33924293, 2021). "Despite that, we revealed that HK2 and HK1 levels correlate in patient-derived ovarian epithelial cancer cells as well as fibroblasts from normal adjacent ovaries." (PMID 34895333, 2021).
ovarian carcinoma (continued). "We found that after infection with shPGC1α and the simultaneous addition of cisplatin, the mitochondrial localization of HK2 and the binding of HK2 and VDAC1 in ovarian cancer drug-resistant cells decreased and apoptosis increased." (PMID 33802591, 2021). "In ovarian cancer models, LPA induces a shift towards glycolysis, upregulates hexokinase 2, and induces metabolic reprograming via a pseudo-hypoxic response that is HIF1α-mediated." (PMID 33671212, 2021). "We tested the isoenzyme-specific regulatory roles of HKs in ovarian cancer cells by examining the effects of the deletions of HK1 and HK2 in TOV-112D ovarian adenocarcinoma cells." (PMID 34895333, 2021). "CT inhibited the expression of glycolysis-related proteins including glucose transporter 1 (GLUT1), hexokinase 2 (HK2), and lactate dehydrogenase A (LDHA) in ovarian cancer Hey cells and xenograft nude mice by repressing STAT3/SIRT3/HIF-1α signaling pathway." (PMID 32265690, 2020). "We also revealed that HK2 controls a metabolic switch, which promotes cell migration, invasion, CSC properties, proliferation, and anchorage-independent growth in ovarian cancer cells." (PMID 31212816, 2019). "We first detected the specific transient (siHK2) and stable (shHK2) knockdown of HK2 in A2780CP and ES-2 cell lines, ovarian cancer cell lines with relatively high HK2 expression." (PMID 31212816, 2019). "Western blotting showed that GSK690693 blocked the miR-29b silencing-induced activation of AKT2/3, HK2 and PKM2, confirming that the miR-29b-AKT axis regulates the activity of key glycolytic enzymes in ovarian cancer cells." (PMID 26512921, 2015). "HK2 acts as a mediator to facilitate glucose metabolic reprogramming, thereby enhancing the malignant potential and promoting cell autophagy through FAK/MAPK kinase signaling to confer resistance against cisplatin therapy in ovarian cancer stem cells." (PMID 38577616, 2024). "Moreover, HK2 expression was observed in ovarian cancer cell lines (OVCA433, A2780 and SKOV3) using immunocytochemistry and western blotting, and a relatively low expression of HK2 was observed in OVCA433 and SKOV3 cells." (PMID 35711830, 2022). "Furthermore, TRPM7 silencing also decreased the relative levels of glycolysis-related HK2 and PDK1 expression as well as PKM2 nuclear translocation, but increased OXPHOS-related IDH3B and UQCRC1 expression in ovarian cancer cells and tissues." (PMID 35101076, 2022). "The positive correlation between HK2 and p-Akt1 (r = 0.4979, p = 0.0105), fibronectin (r = 0.1850, p = 0.0320) and MMP9 (r = 0.3821, p = 0.0020) in these human ovarian cancer tissues was confirmed by using Pearson correlation analysis." (PMID 35953860, 2022). "In ovarian cancer, SIK2 upregulates HIF-1α, which then increases glycolytic enzyme HK2 translation." (PMID 36230617, 2022). "In terms of mRNAs, one study based on Gene Expression Omnibus (GEO) and The Cancer Genome Atlas (TCGA) databases demonstrates the positive correlations between ovarian cancer biomarkers (such as CD44) and glycolytic biomarkers (such as hexokinase 2 (HK2), lactate dehydrogenase A (LDHA), and ENO1)." (PMID 35498135, 2022). "Additionally, the positive correlation between HK2 and fibronectin, MMP9, CHD2, Vemintin, ZEB1 and ZEB2 in human ovarian cancer were also confirmed from the GEPIA online database." (PMID 35953860, 2022). "Additionally, the positive correlation between HK2 and fibronectin, MMP9, CHD2, Vimentin, ZEB1 and ZEB2 in human ovarian cancer were confirmed from the GEPIA online database (p < 0.05)." (PMID 35953860, 2022). "HK2 overexpression can regulate lactate production through the expression of MMP9/Nanog/Sox9 mediated by the FAK/ERK1/2 signaling pathway and participates in ovarian cancer metastasis and stem cell regulation." (PMID 36407100, 2022). "We found that the HK1 depletion (but not the HK2 depletion) sensitized ovarian cancer cells to high-dose metformin during glucose starvation." (PMID 34895333, 2021).
ovarian carcinoma (continued). "Based on these results, PGC1α may reduce apoptosis through the HSP70/HK2/VDAC1 signaling pathway, thus promoting cisplatin resistance of ovarian cancer." (PMID 33802591, 2021). "The HK1 deletion (but not HK2 deletion) suppressed the growth of xenotransplanted ovarian cancer cells and nearly abolished the tumor growth when the mice were fed the glucose-free diet." (PMID 34895333, 2021). "Furthermore, HSP70 induces the expression of HK2 in mitochondria and its binding with VDAC1, consequently promoting cisplatin resistance in ovarian cancer." (PMID 33802591, 2021). "For instance, in ovarian cancer, HK2 is highly expressed in cancer tissues compared with normal, benign, and borderline ovarian tumors, suggesting targeting HK2 is a promising approach for cancer treatment." (PMID 32766131, 2020). "HK2 is the first rate-limiting enzyme in the glycolysis process, which promotes cisplatin resistance by enhancing drug-induced and ERK-mediated autophagy in ovarian cancer." (PMID 32685545, 2020). "LND is another inhibitor of HK2, that enhanced CDDP activity in ovarian cancer cells." (PMID 32211323, 2020). "In addition, recently study revealed that HK2 regulated cell migration, invasion, and stemness via FAK-ERK1/2/-MMP9-NANOG-SOX9 signaling cascades in ovarian cancer cells." (PMID 33324557, 2020). "To further evaluate the effect of HK2 and its downstream signaling pathways in ovarian cancer cell migration and invasion, we stably transfected SKOV-3 cells, an ovarian cancer cell line with relatively low HK2 expression, with DDK-tagged HK2 plasmid or control empty vector." (PMID 31212816, 2019). "To explore the possible upstream mechanisms leading to HK2 upregulation in ovarian cancer cells, we determined whether ovarian CAF-CM regulates HK2 expression in SKOV-3 cells." (PMID 31212816, 2019). "Thus, PGC1α may act on mitochondria to regulate the HSP70/HK2/VDAC1 signaling pathway and reduce apoptosis, promoting cisplatin resistance in ovarian cancer." (PMID 38711526, 2024). "Aspirin reduced HK2 expression in a dose-dependent manner subsequently reducing glycolytic rate, the authors suggest that aspirin may be a promising adjuvant therapy for BRCA1 mutant ovarian cancer patients." (PMID 37720350, 2023). "Thus, the biological functions of PRMT5 binding to HK2 or GAPDH deserves further exploration, which would hopefully help us to broader implications for proving PRMT5 as a potential target for the treatment of ovarian cancer." (PMID 36999124, 2023). "Moreover, in order to confirm the positive correlation between the expression of HK2 and p-Akt1, Fibronectin and MMP9 in human ovarian cancer tissues, serial sections of human ovarian cancer tissues (n = 25) were immunostained with antibodies specific for HK2, p-Akt1, fibronectin and MMP9." (PMID 35953860, 2022). "In addition to the effects on cell migration and invasion, we believe our identification of the downstream pathways of HK2—Namely the HK2 to FAK to MEK-1/ERK1/2 pathway that controls NANOG and SOX9 expression and ovarian cancer CSC properties—Will be of significant importance to future studies." (PMID 31212816, 2019). "Since previous reports indicated that HK2-mediated ovarian cancer cell invasion is mediated through the FAK/ERK1/2 pathway, and FAK promotes EMT in cancer cells by upregulating Twist1 and Snail expression, we examined whether HK2 regulates EMT in EC cells in a FAK-dependent manner." (PMID 34174908, 2021). "The “Pathological Stage Plot” module of GEPIA2 was used to analyze the correlation between HK2 expression and the pathological stages of cancers, including CESC, KICH (Kidney Chromophobe), LIHC, ovarian cancer and PAAD (all p < 0.05) but not others." (PMID 36335239, 2022).
ovarian carcinoma (continued). "Although many works report altered expression of glycolysis-related proteins (glucose transporter 1, GLUT1; hexokinase 2, HK2; lactate dehydrogenase A, LDHA) in ovarian cancer, our analysis did not reveal differences in the glucose levels between the studied groups of the samples." (PMID 39456684, 2024).
colorectal cancer (94 papers, 2015 to 2026). A primary or metastatic malignant neoplasm that affects the colon or rectum. "IMP2 is a critical regulator of glycolysis in colorectal cancer, driving tumor progression by stabilizing m6A-modified mRNAs of key glycolytic enzymes, hexokinase 2 (encoding HK2) and SLC2A1 (encoding GLUT1)." (PMID 40141058, 2025). "HK2 inactivation was associated with increased expression of HK1 in colorectal cancer cell lines pointing to the compensation effect." (PMID 28105937, 2016). "HK2 gene inactivation was associated with increased expression of HK1 in colorectal cancer cells." (PMID 28105937, 2016). "Additionally, some scholars have found that knocking out S-phase kinase-associated protein 2 (Skp2) could inhibit HK2 expression and glycolysis, and thereby limit the growth of colorectal cancer cells in vivo and in vitro." (PMID 39991762, 2025). "Collectively, this study uncovers a novel strategy for targeting HK2 to regulate both tumor cell metabolism and the immune microenvironment, providing a potential therapeutic approach for colorectal cancer." (PMID 42158859, 2026). "In this study, we report that baicalin, a flavonoid derived from Scutellaria baicalensis, acts as a HK2 inhibitor and exerts anti-colorectal cancer activity." (PMID 42158859, 2026). "This preservation of HK2 enhances glycolysis, thereby augmenting anti-tumor immunity in melanoma and colorectal cancer." (PMID 41488637, 2025). "Down-regulated FTO and ALKBH5 co-operatively activate FOXO signaling through m6A methylation modification in HK2 mRNA mediated by IGF2BP2 to enhance glycolysis in colorectal cancer." (PMID 40428320, 2025). "METTL3 has been shown to stabilize HK2 expression in colorectal cancer through an m6A-IGF2BP2/3 dependent mechanism, thereby further regulating glycolytic metabolism and cell proliferation." (PMID 39991762, 2025). "For instance, in oxaliplatin-resistant colorectal cancer cells, the expression of hexokinase 2 (HK2) and lactate dehydrogenase A (LDHA) is markedly upregulated, thereby enhancing glycolytic flux and reducing intracellular drug accumulation." (PMID 41229498, 2025). "Treatment with IL-6 promotes expression of the glycolytic genes SLC2A1, HK2, PKM2, PFKFB3, and LDHA in human colorectal cancer cells, and similarly induces Hk2, Pkm2, and Pfkfb3 expression in murine macrophages." (PMID 39433211, 2025). "It is noteworthy that research has revealed the phenomenon of high expression of HK2 in many cancer tissues or cells, such as colorectal cancer 18, brain metastases tumor 19, and pancreatic cancer." (PMID 39991762, 2025). "For instance, Xanthohumol has been shown to inhibit colorectal cancer cells by downregulating HK2-mediated glycolysis." (PMID 40756987, 2025). "In colorectal cancer, B7-H3 increases glucose consumption and promotes hexokinase 2 (HK2) expression, leading to lactate production and enhanced resistance to platinum and 5-Fu." (PMID 40093000, 2025). "Kaempferol concurrently downregulates HK2 protein expression, inhibiting the uptake of glucose by colorectal cancer (CRC) cells and consequently decreasing the levels of the HBP pathway substrate UDP-GlcNAc." (PMID 40959291, 2025). "KIAA1429 can promote aerobic glycolysis including increasing glucose uptake and lactate production by up-regulating HK2 (hexokinase 2, a crucial enzyme in aerobic glycolysis) expression in an m6A-dependent manner in colorectal cancer." (PMID 39456252, 2024). "The increased expression and half-life of c-Myc protein can activate the β-TrCP/c-Myc/HK2 pathway, enhance glycolysis in colorectal cancer, significantly increase intracellular lactate, and promote the progression of colorectal cancer." (PMID 39609317, 2024). "This interaction enhances glycolysis in colorectal cancer (CRC) cells through the c-Myc/HK2 signaling pathway, ultimately amplifying the malignant behavior of these cells (Schematic model)." (PMID 39003255, 2024).
colorectal cancer (continued). "miR-761 and miR-1224–5p, which are both sponge targets of LOXL1-AS1, share a common target gene, HK2, in colorectal cancer." (PMID 39136001, 2024). "LncRNA FGD5-AS1 promotes glycolysis through modulating the miR-330-3p-HK2 axis, leading to 5-Fu resistance of colorectal cancer cells." (PMID 38806777, 2024). "Xenografted colorectal cancer cells overexpressing B7-H3 were more resistant to oxaliplatin while treatment with 2-Deoxy-D-glucose (2-DG), an HK2 inhibitor, reduced tumor size and tumor regrowth rate." (PMID 37779896, 2023). "B7-H3, an immunoregulatory protein, was found to confer resistance to oxaliplatin and 5-FU in colorectal cancer cell lines through upregulation of hexokinase 2 (HK2) leading to increased glucose and lactate consumption." (PMID 37779896, 2023). "miR-590-5p has been found to suppress malignant melanoma cell growth and invasions by targeting Skp2 and downregulation of circ-PITHD1 can inhibit colorectal cancer through suppression and the miR-590-5p/HK2 axis." (PMID 37540226, 2023). "Increased Hk2 and Glut1 mRNA stability subsequently led to the activation of glycolysis and promoted colorectal cancer cell progression." (PMID 35350378, 2022). "MiR-513a-5p restrains the proliferation and glycolysis of colorectal cancer cells by repressing hexokinase 2 expression." (PMID 34903127, 2021). "It has been reported that B7-H3 promotes aerobic glycolysis and increases chemoresistance in colorectal cancer cells through the upregulation of HK2." (PMID 34217310, 2021). "The HK2/TIGAR complex lowers mitochondrial ROS levels, stimulates HK2 activity and protects colorectal carcinoma cells from death." (PMID 33946854, 2021). "METTL3 acts as an oncogene in colorectal cancer via its interaction with the glycolysis components, hexokinase 2 (HK2) and glucose transporter 1 (GLUT1) mRNAs, in an m6A-dependent manner." (PMID 32709063, 2020). "The connection between miR-143 and HK2 has been studied also in colorectal cancer, where it has been shown that it downregulates HK2 expression and that its reintroduction leads to a decrease in lactate secretion by impairing the rate of glycolysis." (PMID 32486505, 2020). "We further demonstrate that KCNQ1OT1 levels positively correlate with HK2 expression and prognosis in colorectal cancer patients." (PMID 32564010, 2020). "ATOH8 then transcriptionally activated HK2-mediated glycolysis, thus promoting the intravascular survival of colorectal cancer cells in the circulation." (PMID 32000836, 2020). "Taken together, these findings demonstrate that KCNQ1OT1 modulates colorectal cancer proliferation by enhancing aerobic glycolysis through HK2." (PMID 32564010, 2020). "Traditionally, it has been believed that the expression level of hexokinases, especially HK2, is increased in colorectal cancer." (PMID 30967137, 2019). "Altogether, these findings suggest that STAT3 is a direct transcriptional activator for HK2 in human colorectal cancer." (PMID 31655629, 2019). "In the present study, we have shown that HK2 is highly expressed in human colorectal cancer tissues and cell lines." (PMID 31595166, 2019). "Taken together, our results suggest HK1 and HK2 genes as the potential molecular targets for colorectal cancer and melanoma therapy." (PMID 28105937, 2016). "We have demonstrated that simultaneous inactivation of HK1 and HK2 was sufficient to decrease proliferation and viability of melanoma and colorectal cancer cells." (PMID 28105937, 2016). "Our data demonstrate for the first time that NDRG2 inhibits glycolysis in colorectal cancer cells by inhibiting glucose transporter 1, catalytic enzymes HK2, PKM2, LDHA." (PMID 26317652, 2015). "However, other research indicated that ATOH8 promoted vascular survival of colorectal cancer cells through transcriptional activation of HK2-mediated glycolysis." (PMID 40282270, 2025). "The other targets of LOXL1-AS1 are miR-1224–5p and miR-761, targeting HK2 in colorectal cancer." (PMID 39136001, 2024).